SCGB3A2 (secretoglobin family 3A member 2)
Diseases named in the same sentence as SCGB3A2 in open-access papers (continued):
Sharing a sentence is not in itself a finding about the gene and the disease.
cancer (8 papers, 2018 to 2025). A tumor composed of atypical neoplastic, often pleomorphic cells that invade other tissues. "Further work is also needed to understand in more detail how SCGB3A2 and LPS work together to cause cancer cell death." (PMID 30526845, 2018). "Secretoglobin family 3 A member 2 (SCGB3A2) is a small secretory protein mainly found in the Club cells of the airway epithelial and has several biological functions, including anti-cancer and anti-fibrotic features." (PMID 41291696, 2025). "The results highlight the importance of SCGB3A2 in some cancer cells to trigger their pyroptotic cell death, demonstrating a promising function of SCGB3A2 as an inhibitor of cancer cell growth." (PMID 33452234, 2021). "Our results highlight a critical role for SCGB3A2 in eliminating cancer cells through the same mechanism used to eliminate pathogens." (PMID 33452234, 2021). "In conclusion, SCGB3A2 uses the machinery of the pyroptotic cell death for the elimination of SDC1/CASP4-positive human cancer cells." (PMID 33452234, 2021). "However, as our results demonstrate, some cancer cells undergo pyroptosis in vivo upon exposure to cytosolic LPS delivered by SCGB3A2, in addition to its immunomodulatory function." (PMID 33452234, 2021). "SCGB3A2-LPS treatment may provide a tool to treat this group of cancer patients." (PMID 33452234, 2021). "Cell communication analysis indicated strong interactions between CD2AP+ cancer cells and monocytes, predominantly mediated by the APP-CD74, MIF-CD74_CD44, and SCGB3A2-MARCO pathways." (PMID 41425578, 2025). "However, the role of SCGB3A2 in cancer development is unknown." (PMID 31616642, 2019). "Based on these results, we propose a new model for SCGB3A2 delivery of LPS and activation of caspase-11(caspase-4) pathway via SDC1 receptor signaling, leading to pyroptosis of cancer cells." (PMID 30526845, 2018). "SCGB3A2 and LPS co-treatment significantly induced pyroptosis of macrophage RAW264.7 cells and decreased cancer cell proliferation in vitro, while SCGB3A2 treatment resulted in reduced progression of xenograft tumors in mice." (PMID 30526845, 2018). "Furthermore, we previously demonstrated that SCGB3A2 (also called UGRP1 (uteroglobin-related protein 1)), another member belonging to the same SCGB3A gene subfamily as SCGB3A1, is a ligand for Syndecan-1 (SDC1) in cancer cells." (PMID 41469838, 2025). "However, whether SCGB3A2 also inhibits human cancer cells growth by means of pyroptosis has not been explored yet." (PMID 33452234, 2021). "Thus, the rare mutation rate and the ability to activate pyroptotic process of CASP4 in the SCGB3A2-inducded non-canonical inflammasome pathway could be utilized as a new strategy for human cancer therapy." (PMID 33452234, 2021). "The role of SCGB3A2 as a chaperon to deliver LPS to cell cytosols may initially be established to protect host cells from infection, while this mechanism may have evolved to protect host from cancer development by activation of the non-canonical inflammasome signaling pathway." (PMID 30526845, 2018).
infection (5 papers, 2018 to 2023). The state of being infected such as from the introduction of a foreign agent such as serum, vaccine, antigenic substance or organism. "Interestingly, Krt5-immunoreactive pods observed in lungs of either IL-22 LOF or IL-22r cLOF mice 14 days post-PR8 infection displayed evidence for Scgb3a2 expression that was absent in comparable Krt5-immunoreactive pod structures of wildtype control mice." (PMID 37726288, 2023).
inflammation (3 papers, 2014 to 2015). Aberrant reaction of the microcirculation characterized by movement of fluid and leukocytes from the blood into extravascular tissues. "Previous reports demonstrated that the levels of pro-inflammatory cytokines, IL-4, IL-5, and IL-13, and airway inflammation were suppressed in mice pre-treated with SCGB1A1 or SCGB3A2 in the OVA-induced allergic airway inflammation model." (PMID 26559674, 2015). "When OVA-induced airway inflammation model mice were intranasally administered recombinant adenovirus expressing SCGB3A2 before OVA challenge, OVA-induced airway inflammation was suppressed." (PMID 26178733, 2015). "Further, in the ovalbumin (OVA)-induced airway inflammation model mice, reduced levels of lung Scgb3a2 mRNA were inversely correlated with the increased levels of proinflammatory cytokines, IL-5 and IL-9 in bronchoalveolar lavage fluid (BALF)." (PMID 26178733, 2015). "Further, when OVA-airway inflammation model mice were intranasally administered recombinant adenovirus expressing SCGB3A2 before OVA challenge, OVA-induced airway inflammation was suppressed with airway overexpression of SCGB3A2." (PMID 25242865, 2014). "Further, the anti-inflammatory activity of SCGB3A2 was demonstrated by the intranasal administration of recombinant adenovirus expressing SCGB3A2 to the OVA-induced inflammation model mouse, in which forced airway expression of SCGB3A2 suppressed OVA-induced airway inflammation." (PMID 26559674, 2015).
adenocarcinoma (1 paper, 2016). A common cancer characterized by the presence of malignant glandular cells. "Immunohistochemistry for SCGB3A2 revealed that this protein was expressed in 74% of primary lung tumors and was predominantly expressed in adenocarcinomas (86%)." (PMID 26654940, 2016).
SCGB3A2 also shares sentences with these, for which no sentence is quoted: allergic disease (4 papers); Allergy (3); rhinitis (3); Lewis lung carcinoma (2); lung squamous cell carcinoma (2); age (1); allergic rhinitis (1); autoimmune thyroid disease (1); colorectal tumor (1); cystic fibrosis (1); hepatocellular carcinoma (1); idiopathic pulmonary fibrosis (1); influenza (1); interstitial lung disease (1); metastatic disease (1); nasal polyps (1); ovarian carcinoma (1); pneumococcal pneumonia (1); pneumonia (1); sarcoidosis (1); schizophrenia (1); Sepsis (1); small cell lung carcinoma (1); Streptococcus pneumoniae infection (1); type 1 diabetes mellitus (1).